CPNE4 (copine 4)
Description:
Probable calcium-dependent phospholipid-binding protein that may play a role in calcium-mediated intracellular processes.
Synonyms: COPN4; CPN4
Tractability: Antibody: its Gene Ontology location is reachable by antibodies, with medium confidence. PROTAC: its protein half-life has been measured.
Gene: Protein-coding gene on chromosome 3 (131,533,555 to 132,285,410, reverse strand). Ensembl gene ENSG00000196353.
Subcellular location (Human Protein Atlas): Cytosol; Nucleoplasm
Gene Ontology:
Molecular function: protein binding; calcium-dependent phospholipid binding
Biological process: cellular response to calcium ion
Cellular component: extracellular exosome; glutamatergic synapse; synapse
Genetic constraint (gnomAD): Loss-of-function variants: 17 observed, 47.22 expected, observed/expected ratio (o/e) 0.36, 90% interval 0.25 to 0.54. The upper end of that interval is the gene's LOEUF score, 0.54, which puts it in group 2 of 6, group 1 being the genes least tolerant of losing a copy. Missense variants: 395 observed, 615.2 expected, observed/expected ratio (o/e) 0.64, 90% interval 0.59 to 0.7. Synonymous variants: 212 observed, 224.58 expected, observed/expected ratio (o/e) 0.94, 90% interval 0.84 to 1.06.
Homologues: Orthologues: chimpanzee CPNE4 (100% identical), macaque CPNE4 (100% identical), dog CPNE4 (99% identical), pig CPNE4 (99% identical), guinea pig CPNE4 (99% identical), mouse Cpne4 (99% identical), rat Cpne4 (99% identical), rabbit CPNE4 (99% identical), tropical clawed frog cpne4 (93% identical), zebrafish cpne4b (88% identical), zebrafish cpne4a (86% identical), Caenorhabditis elegans cpna-2 (43% identical), and 3 more. Paralogues in human: CPNE7 (69% identical), CPNE6 (61% identical), CPNE3 (54% identical), CPNE2 (51% identical), CPNE8 (51% identical), CPNE5 (50% identical), CPNE1 (49% identical), CPNE9 (48% identical).
Diseases named in the same sentence as CPNE4 in open-access papers:
CPNE4 is named in the same sentence as 9 diseases in open-access papers, as found by Europe PMC text mining. Sharing a sentence is not in itself a finding about the gene and the disease. The quoted sentences say what the papers report.
colon cancer (1 paper, 2018). "For instance, CPNE4 and EPHA7 are already shown to be involved in colon cancer." (PMID 29589558, 2018).
cancer (1 paper, 2018). A tumor composed of atypical neoplastic, often pleomorphic cells that invade other tissues. "In contrast, some of the genes, including ENTHD1, HELZ2, PCDH12, CPNE4, and SHANK1, that are mutated in metastatic ACCs alone are completely novel and have not been functionally characterized in any cancer type until now." (PMID 30301885, 2018).
neurodegenerative disease (1 paper, 2019). A disorder of the central nervous system characterized by gradual and progressive loss of neural tissue and neurologic function. "Some polymorphisms in the CPNE4 gene have been associated with cardiovascular and neurodegenerative diseases." (PMID 31766143, 2019).
tumor (1 paper, 2025). "The commonly overexpressed genes that may be involved in tumor secretion include SCIN (scinderin) and CPNE4 (calcium-dependent phospholipid-binding protein)." (PMID 40002253, 2025).
CPNE4 also shares sentences with these, for which no sentence is quoted: breast carcinoma (1 paper); HIV-1 infection (1); multinodular goiter (1); salpingitis (1); type 2 diabetes (1).